ETS1 (ETS proto-oncogene 1, transcription factor)
Description:
Transcription factor. Directly controls the expression of cytokine and chemokine genes in a wide variety of different cellular contexts. May control the differentiation, survival and proliferation of lymphoid cells. May also regulate angiogenesis through regulation of expression of genes controlling endothelial cell migration and invasion. [Isoform Ets-1 p27]: Acts as a dominant-negative for isoform c-ETS-1A.
Synonyms: EWSR2; FLJ10768; ETS-1; c-ets-1; p54
Tractability: Small molecule: it has a high-quality binding pocket. PROTAC: UniProt records ubiquitination sites on it; ubiquitination databases record sites on it; its protein half-life has been measured.
Gene: Protein-coding gene on chromosome 11 (128,458,761 to 128,587,606, reverse strand). Ensembl gene ENSG00000134954.
Subcellular location: Nucleus; Cytoplasm
Subcellular location (Human Protein Atlas): Nucleoplasm
Pathways (Reactome):
Cellular responses to stimuli: Oncogene Induced Senescence
Developmental Biology: Differentiation of naive CD4+ T cells to T helper 2 cells (Th2 cells)
Gene Ontology:
Molecular function: DNA-binding transcription activator activity, RNA polymerase II-specific; DNA-binding transcription factor activity; DNA-binding transcription factor activity, RNA polymerase II-specific; identical protein binding; nucleic acid binding; protein binding; RNA polymerase II cis-regulatory region sequence-specific DNA binding; RNA polymerase II-specific DNA-binding transcription factor binding; transcription cis-regulatory region binding; transcription corepressor binding; DNA binding; sequence-specific DNA binding; sequence-specific double-stranded DNA binding
Biological process: cell motility; PML body organization; positive regulation of angiogenesis; positive regulation of blood vessel endothelial cell migration; positive regulation of DNA-templated transcription; positive regulation of endothelial cell migration; positive regulation of erythrocyte differentiation; positive regulation of gene expression; positive regulation of inflammatory response; positive regulation of leukocyte adhesion to vascular endothelial cell; positive regulation of miRNA transcription; positive regulation of transcription by RNA polymerase II; regulation of angiogenesis; cell differentiation; immune response; negative regulation of cell population proliferation; regulation of transcription by RNA polymerase II; regulation of DNA-templated transcription
Cellular component: cytoplasm; nucleoplasm; nucleus; chromatin
Genetic constraint (gnomAD): Loss-of-function variants: 10 observed, 43.16 expected, observed/expected ratio (o/e) 0.23, 90% interval 0.14 to 0.39. The upper end of that interval is the gene's LOEUF score, 0.39, which puts it in group 1 of 6, group 1 being the genes least tolerant of losing a copy. Missense variants: 343 observed, 503.22 expected, observed/expected ratio (o/e) 0.68, 90% interval 0.62 to 0.75. Synonymous variants: 177 observed, 185.84 expected, observed/expected ratio (o/e) 0.95, 90% interval 0.84 to 1.08.
Gene-disease validity (ClinGen):
ClinGen rates the evidence that ETS1 causes each of these diseases.
congenital heart disease (autosomal dominant): Moderate. A heart disease that is present at birth.
Homologues: Orthologues: chimpanzee ETS1 (99% identical), macaque ETS1 (99% identical), dog ETS1 (97% identical), rabbit ETS1 (97% identical), pig ETS1 (95% identical), rat Ets1 (94% identical), mouse Ets1 (94% identical), guinea pig ETS1 (84% identical), tropical clawed frog ets1 (81% identical), zebrafish ets1 (43% identical). Paralogues in human: ETS2 (49% identical), FLI1 (26% identical), ERG (26% identical), GABPA (24% identical), ETV1 (22% identical), ETV5 (22% identical), ETV2 (20% identical), ETV4 (20% identical), ETV6 (19% identical), SPDEF (17% identical), ELF2 (16% identical), ETV7 (16% identical), and 16 more.
Diseases named in the same sentence as ETS1 in open-access papers:
ETS1 is named in the same sentence as 273 diseases in open-access papers, as found by Europe PMC text mining. Sharing a sentence is not in itself a finding about the gene and the disease. The quoted sentences say what the papers report.
breast carcinoma (117 papers, 2004 to 2025). "In breast cancer, high expression of ETS-1 is closely associated with poor prognosis, increased malignancy, and invasiveness." (PMID 40181983, 2025). "Among these, only ETS1 showed a strong negative correlation with ACVR1B and a positive correlation with MGAT5 in TCGA pancreatic and breast cancer cohorts, implicating ETS1 in ALK4 loss-mediated MGAT5 upregulation." (PMID 41408046, 2025). "ETS1 has been implicated in various cancers, including lung and breast cancer, where it cooperates with other transcription factors like ETS2 to influence gene expression related to cell invasion and metastasis." (PMID 40938895, 2025). "Activation of Ets-1 in cancers is highly associated with chemoresistance and linked to poor prognosis in ovarian cancer, breast cancer, and lung adenocarcinoma." (PMID 35789155, 2022). "Ets-1 was found to be overexpressed in breast cancer, which was reported to be associated with poor prognosis." (PMID 33671331, 2021). "The miRNA-mRNA network shows that significantly deregulated miRNAs in the FS and FSO groups target genes involved in the MG development (red circles) and/or associated with breast cancer (blue circles), including Egfr, Igf-1, Igf-1R, Hif1a, Ets1, and pgr." (PMID 31689992, 2019). "Deletion of CRE region down-regulated Ets1 expression and, consequently, reduced breast cancer progression by altering cancer-associated genetic programs." (PMID 30467308, 2018). "ETS1 gene expression has been associated with tumor progression in various tumors such as thyroid, pancreas, liver, lung and breast carcinomas, and melanoma." (PMID 27449293, 2016). "Among ETS family proteins, ETS-1 is highly expressed in breast cancer, ovary cancer, and cervical carcinomas and is associated with a poor prognosis." (PMID 24857950, 2014). "Fatty acid desaturation by the delta-5 and delta-6 desaturases upregulated by Ets-1 in this study, fatty acid desaturase-1 and −2, result in the production of arachidonic acid, which is associated with breast cancer progression, metastasis and angiogenesis." (PMID 24280356, 2013). "In summary, NO signaling results in the activation of the oncogenic transcription factor Ets-1, which is critical for the basal-like breast cancer phenotype associated with tumor NOS2 expression." (PMID 22971289, 2012). "Ets-1 overexpression in breast cancer is associated with more invasive tumors and a significantly poorer prognosis." (PMID 20454645, 2010). "Similarly, hsa-miR-199b, which influences neutrophils through ETS1 expression, has previously been implicated in breast cancer, and described as a tumor suppressor in acute myeloid leukemia and an inducer of apoptosis in oral cancer." (PMID 37303042, 2023). "A high level of ETS-1 protein is associated with poor breast cancer prognosis." (PMID 29312607, 2017). "Ets-1, V-ets erythroblastosis virus E26 oncogene homolog 1, is suppressed by miR-199a-5p, the loss of which may promote breast cancer cell invasion." (PMID 29137361, 2017). "Thus, increases in breast cancer angiogenesis associated with Ets1 are likely due to elevated Ets1 expression in endothelial cells." (PMID 23874775, 2013). "Additionally, to investigate the ability of our findings to extend to other types of human cancer, we developed an Ets-1 knockdown model in MDA-MB-231 breast cancer cells, as aggressive breast cancer is frequently associated with the overexpression of Ets-1." (PMID 24280356, 2013). "Ets-1 signaling has also been linked to the development of a basal-like breast cancer phenotype." (PMID 22971289, 2012). "The ETS1 signaling pathway was found to promote tumor cell migration, invasion, and secretion of matrix metalloproteinases (MMPs), which was closely associated with lymph node metastasis and distant metastasis in patients with lung, colon, ovarian, and breast cancers." (PMID 35003395, 2021).
breast carcinoma (continued). "We next performed the same experiment using MCF‐7, a human breast cancer cells, which have been proved to express a very low levels of Ets‐1." (PMID 39778077, 2025). "Next, we analyzed the accumulation of oxidative DNA lesions and the levels of DNA damage‐related proteins in Ets‐1‐overexpressing and Ets‐1‐non‐expressing breast cancer cells after treatment with different PARPi." (PMID 39778077, 2025). "As an oncogene, Ets1 acts in colorectal cancer, breast cancer, and hepatocellular carcinoma by targeting A variety of microRNAs (such as miR‐125p and miR‐139‐5p), providing evidence that Ets1 is important in tumorigenesis." (PMID 40887825, 2025). "The mechanism of the antitumor effect of PARP‐1 inhibition was investigated in the Ets‐1‐expressing MDA‐MB‐231 breast cancer cells." (PMID 39778077, 2025). "This preliminary study supports the effectiveness of PARPi in Ets‐1‐expressing breast cancer cells and reveals the possible mechanism of oxidative DNA damage induction through PARP‐1 inhibition." (PMID 39778077, 2025). "These preliminary findings correlate PARPi‐induced oxidative DNA damage/oxidative stress to Ets‐1 expression in breast cancer cells." (PMID 39778077, 2025). "Clinical studies have shown that knockdown of ETS1 inhibits cell transformation and reverses multidrug resistance in breast cancer cells." (PMID 40948762, 2025). "The expression of ETS-1 varies across different tumor types, with notable overexpression in several solid tumors, including breast cancer, prostate cancer, lung cancer, and colorectal cancer." (PMID 40181983, 2025). "We suggest that the inhibition of PARP‐1, which it is known to induce Ets‐1 accumulation, increases oxidative DNA damage only in breast cancer cells expressing Ets‐1." (PMID 39778077, 2025). "Among 36 breast cancer cell lines, ETS1 expression negatively correlated with dasatinib IC50 values (r = −0.6054, p < 0.0001)." (PMID 41462902, 2025). "In prostate and breast cancer, it is a marker of poor prognosis, while ETS1 is downregulated in poorly differentiated pancreatic adenocarcinoma." (PMID 39941022, 2025). "For instance, miR-338-5p was found to be able to affect the proliferation and metastasis of breast cancer by acting on the transcription factor ETS1 of Notch1, and this has been demonstrated in breast cancer tissues as well as xenograft tumor models." (PMID 40486870, 2025). "This was confirmed in studies conducted in patients with breast cancer, which showed that increased S-nitrosylation leads to the activation of Ets-1 caused by MAPK-dependent phosphorylation and results in development of more aggressive breast cancer phenotype." (PMID 37503318, 2023). "ESE1 and ETS1 are dominantly present in luminal and basal-like subtypes of breast cancer cells, and reciprocally regulate each other, thus impacting the EMT status of these cells." (PMID 36864480, 2023). "ELF3, in turn, can repress upregulation of ZEB1/2 by ETS1 in breast cancer, head and neck squamous carcinoma and in normal bile duct epithelial cells." (PMID 36864480, 2023). "For instance, hsa-miR-532-3p acts as a tumor suppressor and inhibits cell proliferation in lung cancer, breast cancer, ovarian cancer and renal cell carcinoma by targeting ETS1." (PMID 37848987, 2023). "Adding to our finding that ectopic expression of PTPN18 resulted in dephosphorylation of ETS1 and promoted its degradation, we further delineated the role of nuclear PTPN18 in regulating breast cancer metastasis by gain/loss-of-function experiments." (PMID 35982039, 2022). "Particularly, ETS proto-oncogene 1 (ETS1) is a known oncogenic transcription factor overexpressed in breast cancer that is driven by the mitogen-activated protein kinase (MAPK)." (PMID 35739379, 2022). "On the other hand, in human breast cancer cells, silencing Ets-1 suppressed colony growth both in anchorage-independent assays and 3D cultures, suggesting a complex regulation of Ets-1 function depending on the biological environment." (PMID 35789155, 2022).
breast carcinoma (continued). "While the mechanisms by which Ets-1 accomplishes these opposing roles are not fully understood, one study showed that in breast cancer, Ets-1 inhibits tumorigenesis via inducing transcription of tumor-suppressor genes." (PMID 35789155, 2022). "The expression of ZEB1 is reportedly regulated by Ets1 in breast cancer cells and positively correlated with the mesenchymal phenotypes in breast cancer and OSCC cells." (PMID 35451213, 2022). "Ets-1 is not only a critical regulator of invasion, but is also involved in regulating cancer energy metabolism in ovarian and breast cancer cell lines." (PMID 33671331, 2021). "In breast cancer, S-nitrosylation of Ras induces MAPK-dependent phosphorylation and activates ETS-1 (Erythroblastosis virus transcription factor-1), a critical mediator of nitric oxide, resulting in an aggressive breast cancer phenotype." (PMID 35006426, 2021). "Accordingly, a previous study conducted in breast cancer has shown that overexpression of ETS1 in the presence of epidermal growth factor (EGF) enhances MMP-9 promoter activity." (PMID 34023818, 2021). "The next pathway, ESR1, which was mutated in breast cancer, received microenvironment factor S100A4 to regulate TF ETS1 and SMAD3 through signaling transduction proteins ZNF516, PIK3R1, IDH1, and AKT1." (PMID 33802957, 2021). "Altogether, these data indicate dichotomous functions of ETS1 as anti-tumorigenic factors through direct activation of targets but also trans-activating other tumor suppressor genes in breast cancer cells." (PMID 32477936, 2020). "Taken together, our study enlightens a novel function of ETS1 as a tumor suppressor in breast cancer cells." (PMID 32477936, 2020). "Analysis of human breast cancer specimens showed a lower level of ETS1 through hyper-DNA methylation on the ETS1 promoter region in BRCA compared to normal specimens, which was closely correlated with poor prognosis in a large number of BRCA patients." (PMID 32477936, 2020). "We utilized the Cancer Genome Atlas (TCGA) database to analyze comprehensive functions of ETS1 in human breast cancer (BRCA) patients by investigating its expression patterns and methylation status in relation to clinical prognosis." (PMID 32477936, 2020). "Altogether, these results indicate that ETS1 suppresses proliferation and growth of breast cancer cells in vitro as well as in vivo." (PMID 32477936, 2020). "Consistently, significantly curtailed expression of ETS1 in breast cancer specimens (n = 1,992) was observed in BRCA specimens compared to normal specimens (n = 144)." (PMID 32477936, 2020). "ETS1 directly bound in genomic loci of these regulators and activated their transcription in breast cancer cells." (PMID 32477936, 2020). "Through the analysis of The Cancer Genome Atlas (TCGA) database, we found that, in contrast to previous studies, breast cancer specimens (n = 1,052) significantly reduced ETS1 expression compared to normal tissues (n = 113)." (PMID 32477936, 2020). "To enlighten down-stream pathways affected by ETS1 in breast cancer cells, we performed Gene Ontology (GO) and found that various tumorigenic pathways, including cell adhesion, angiogenesis, and proliferation, were significantly altered in ΔCRE cells." (PMID 32477936, 2020). "Previously, our group and others have identified up-stream signaling pathways and major transcriptional activators for ETS1 transcription in breast cancer cells." (PMID 32477936, 2020). "To determine how ETS1 regulates proliferation and growth of breast cancer cells, we performed an RNA-sequencing (RNA-seq) based transcriptome analysis with WT and ΔCRE cells." (PMID 32477936, 2020).
breast carcinoma (continued). "In this study, we defined ETS1 as a tumor suppressor that inhibits growth and proliferation of breast cancer cells in both humans and mice." (PMID 32477936, 2020). "To achieve this goal, we employed MDA-MB-231 cells, well-characterized breast cancer cell lines with high levels of ETS1 expression." (PMID 32477936, 2020). "The expression of ETS-1 mRNA is related to the EMT phenotype, which is characterized by vimentin expression and E-cadherin deficiency in breast cancer cell lines." (PMID 32799885, 2020). "For instance, mutation R399Q was found to be positively associated to breast cancer, which is located at the end of the first BRCT domain of XRCC1 and at the interface of the best binding mode predicted by Cluspro in the ETS(Ets-1)/BRCT(XRCC1) docking run." (PMID 30857266, 2019). "Previous studies showed that silencing ETS-1 increased cell proliferation in vitro and reduced tumor growth in vivo in some breast cancer cell lines." (PMID 31118072, 2019). "The negative correlation between hsa_circ_001783 and miR-200c-3p and positive correlation between hsa_circ_001783 and ZEB1, ZEB2, and ETS1 were further observed in the tumor tissues from breast cancer patients." (PMID 30670688, 2019). "An increasing number of studies demonstrated that ETS-1 stability and transcription activity were regulated by phosphorylation of multiple protein kinases in lung and breast cancers." (PMID 31118072, 2019). "For example, Ets-1 cooperates with Smad3 to stimulate the expression of parathyroid hormone-related protein (PTHrP) in breast cancer cells." (PMID 31189885, 2019). "ETS-1 also regulated resistance to other therapies, including androgen receptor inhibitor and paclitaxel in prostate and breast cancers, respectively." (PMID 31118072, 2019). "Recently, it was also shown that SRC phosphorylation of ETS-1 at tyrosine 283 released COP1 degradation of ETS-1 in breast cancer." (PMID 31118072, 2019). "It has been reported that SRC is activated and regulates tumorigenesis through phosphorylation of ETS-1 in breast cancer." (PMID 31118072, 2019). "Data concerning the tumor promotive role of ETS1 in a variety of tumors has been accruing, such as in gastric cancer, breast cancer and glioma." (PMID 31823805, 2019). "Deletion of NFAT and NF-κB binding sites (−540 bp to −270 bp from TSS) within the CRE region (−540 to −80) in metastatic breast cancer cells (ΔCRE cells) diminished Ets1 levels and reduced expression levels of invasion related genes." (PMID 30467308, 2018). "In summary, our study suggests that the crosstalk between NFATc2, NFKB1/RELA, and CRE region regulates Ets1 gene transcription in metastatic breast cancer cells." (PMID 30467308, 2018). "K–M curve showed that the median survival of breast cancer patients in ETS1 low-expression group was 8.3 months, significantly longer than that in high-expression group with 4.4 months (P = 0.0112)." (PMID 29950928, 2018). "In this study, we investigated the transcriptional and epigenetic regulation of Ets1 gene expression in metastatic breast cancer cells." (PMID 30467308, 2018). "In drug-resistant MCF-7 breast cancer cells, ETS1 is overexpressed and results in up-regulation of MDR1." (PMID 29950928, 2018). "Collectively, these data demonstrate a critical role of CRE in Ets1 gene expression and Ets1-mediated metastasis of breast cancer cells." (PMID 30467308, 2018). "To understand the transcriptional regulation mechanisms of Ets1 expression in breast cancer cells, we first analyzed Ets1 transcript level among various breast cancer cell lines." (PMID 30467308, 2018). "We analyzed 1000 human breast cancer specimens and 59 human breast cancer cell lines and found that levels of Ets1 expression is well-correlated with Eng and Mmp14 levels, accordingly." (PMID 30467308, 2018). "To verify the functional role of CRE in Ets1-mediated metastasis of breast cancer cells, first we performed in vitro invasion assay." (PMID 30467308, 2018).